APOE (apolipoprotein E)
Diseases named in the same sentence as APOE in open-access papers (continued):
Sharing a sentence is not in itself a finding about the gene and the disease.
Wilson disease (4 papers, 2013 to 2025). A very rare inherited multisystemic disease presenting non-specific neurological, hepatic, psychiatric or osseo-muscular manifestations due to excessive copper deposition in the body. "Several studies have shown that APOE ε4-positive genotype is associated with earlier symptomatic visibility of Wilson’s disease, particularly amongst patients harboring the ATP7B p.H1069Q homozygous patients in women." (PMID 30126847, 2018). "In comparison, APOE-ε3 genotype is associated with a significant delay in the onset of Wilson disease symptoms." (PMID 23720634, 2013). "In individuals with Wilson’s disease, the diminished copper binding affinity of ApoE4 leads to increased oxidative brain damage in those carrying the ApoE-ε4 genotype." (PMID 40143849, 2025). "An ApoE-copper connection was further supported by the finding that in Wilson disease patients with the common H1069Q mutation in the copper transporter ATP7B, an earlier onset of symptoms is associated with the APOE-ε4 genotype." (PMID 23720634, 2013). "Because ApoE proteins can exert an antioxidant effect, and high copper build-up in Wilson’s disease induce tissue damage via generation of free oxygen radicals, it is speculated that ApoE may render a neuroprotective effect in patients with Wilson’s disease." (PMID 30126847, 2018). "ApoE does not function in protecting the brain from oxidative damage resulting from copper build-up in Wilson’s disease, but may play a role in regulating copper accumulation in the brain." (PMID 30126847, 2018). "However, whether ApoE facilitates neuroprotection in Wilson’s disease was not known." (PMID 30126847, 2018).
anxiety disorder (3 papers, 2015 to 2025). A category of psychiatric disorders which are characterized by anxious feelings or fear often accompanied by physical symptoms associated with anxiety. "We lacked harmonized data across all cohorts on antidepressant medication use, lifetime psychiatric history, anxiety disorders, and APOE genotype; residual confounding by these factors is therefore possible." (PMID 41313677, 2025).
aortic regurgitation (3 papers, 2010 to 2024). "Interestingly, while recently measuring the diameter of the aorta through contrast angiography, we incidentally observed aortic regurgitation associated with a larger (~3-fold) valvular thickness in elderly apoE-/- mice." (PMID 22330242, 2012). "The proportion of male mice (96%) with aortic regurgitation (grades 1-4) was significantly higher than of female mice (51%) when grouping ApoE KO and C57 animals (p = 0.0008)." (PMID 20723257, 2010). "Comparatively, in age-matched female ApoE KO and C57 mice, aortic regurgitation was observed in a proportion of 58% and 53%, respectively." (PMID 20723257, 2010). "Using angiography with injection of iodized contrast, we found a remarkable aortic regurgitation in aged ApoE KO and C57 males compared with aged females." (PMID 20723257, 2010). "In conclusion, both normocholesterolemic (C57) and hypercholesterolemic (ApoE KO) elderly mice exhibit aortic regurgitation, but it is of higher proportion in males than in females." (PMID 20723257, 2010). "We observed that male gender is an important factor for the progression of aortic regurgitation in both normocholesterolemic (C57) and hypercholesterolemic (ApoE KO) mice." (PMID 20723257, 2010). "Aortic regurgitation was observed in 92% of the male ApoE KO mice and 100% of the male C57 mice." (PMID 20723257, 2010).
autonomic dysfunction (3 papers, 2021 to 2025). "The relationship of APOE alleles with the remaining features of aS-pathies remains enigmatic (other neuropsychiatric manifestations, autonomic dysfunction, RBD, neuroleptic sensitivity, and so on)." (PMID 38339074, 2024).
bladder tumor (3 papers, 2012 to 2019). "APOE has been shown to interact with the transitional epithelial response gene (TERE1), a tumor suppressor gene, in bladder tumor cells, resulting in increased cell turnover and resistance to apoptosis." (PMID 23094052, 2012).
Bradycardia (3 papers, 2011 to 2025). A slower than normal heart rate (in adults, slower than 60 beats per minute). "We have previously established that high levels of DEE can induce bradycardia and T-wave alterations in mice and that ApoE–/– mice were more susceptible than their genetic background, C57BL/6 mice." (PMID 21524982, 2011).
brain cancer (3 papers, 2020 to 2023). A primary or metastatic malignant neoplasm affecting the brain. "When used to functionalize NP and liposomes, the ApoE-derived peptide facilitates the uptake of these types of carriers, and it has been proposed for applications, such as brain cancer treatment." (PMID 32823499, 2020).
CADASIL (3 papers, 2018 to 2022). "This may represent a cause of some of the CADASIL-related symptoms, as APOE-ε4 carriers show a significant decline in cognitive function by age 69, with the strongest association being seen in APOE-ε4/ε4 individuals." (PMID 36175824, 2022). "Therefore, the p.Arg544Cys mutation appears to cause a less severe CADASIL phenotype, and low pathogenicity of the mutation may allow APOE ε4 genotype to serve as a disease modifier among elderly CADASIL patients." (PMID 33328970, 2020).
cerebral (3 papers, 2004 to 2021). "Apolipoprotein E deficient mice made transgenic for human apolipoprotein E ε4 accumulate excess cerebral amyloid when compared to similarly prepared mice expressing human apolipoprotein E ε3." (PMID 15312232, 2004). "The demographic (age, gender, and APOE ε4 status) and neuropsychological data were assessed for their ability to predict cerebral amyloid positivity." (PMID 33121011, 2020).
cerebral atherosclerosis (3 papers, 2022 to 2023). Atherosclerosis of the cerebral vasculature. "In keeping with this, as indirectly demonstrated by several epidemiological/clinical studies linking the APOe4 variant with cerebral atherosclerosis, a dysfunctional APOe can compromise this function also in the CNS." (PMID 36901834, 2023). "In conclusion, cerebral atherosclerosis can be generated in both apoE KO and WHHL rabbits, but the latter exhibited more lesions." (PMID 35712258, 2022). "Quantitation of the stenosis rate and cellular components of the lesions revealed that cerebral atherosclerosis in WHHL rabbits was severer and the lesions contained more macrophages than that of apoE KO rabbits." (PMID 35712258, 2022). "We conducted the current study using three kinds of hypercholesterolemic rabbits, cholesterol-fed wild-type (WT), apoE KO and WHHL rabbits, to examine the severity of cerebral atherosclerosis." (PMID 35712258, 2022). "In contrast to WT and apoE KO rabbits fed a cholesterol diet, 87% (13/15) of WHHL rabbits exhibited differing degrees of cerebral atherosclerosis in 3 major branches: PCA (43%), BA (73%) and VA (26%), but not in other branches, whereas two rabbits (aged 14 and 27 months) had no lesions." (PMID 35712258, 2022).
chronic headache (3 papers, 2019 to 2022). "In men, APOE-ε4 confers a decreased risk to develop chronic headaches and back pain whereas APOE-ε2 increases the risk to develop chronic abdominal, back, hip, and knee pain." (PMID 35149686, 2022). "L-PGDS, VDBP and APOE had abnormal serum levels in MOH patients, confirming their alteration in some conditions of chronic headache and neuropathic pain." (PMID 31623575, 2019).
chronic heart failure (3 papers, 2012 to 2023). "Apolipoprotein E, tropomyosins, alpha-2 macroglobulin, complement 3, creatin kinase B and ceruloplasmin have been also described as biomarkers for chronic heart failure." (PMID 22384053, 2012).
cognition (3 papers, 2010 to 2022). Intellectual or mental process whereby an organism becomes aware of or obtains knowledge. "A multimodal meta-analysis noted that APOE ε4 carriers presented a higher risk of developing white matter hyperintensity, which had been widely accepted that was clearly associated with cognition decline." (PMID 35847686, 2022).
dilated cardiomyopathy (3 papers, 2021 to 2024). Cardiomyopathy which is characterized by dilation and contractile dysfunction of the left and right ventricles. "Since many studies point out the role of apoE−/− in the development of dilatative cardiomyopathy, we performed histological measurements of heart cavities and walls." (PMID 34575848, 2021). "Whether apoE can affect cardiac fibroblasts and subsequently contribute to the development of dilated cardiomyopathy must be further investigated." (PMID 34575848, 2021). "Since the involvement of apoE in the pathology of dilated cardiomyopathy is still not known, the aim of the study is to investigate the lipid-independent effects of apoE on heart tissue and the possible correlation with non-ischemic heart pathology in animals and humans." (PMID 34575848, 2021).
dystrophin deficiency (3 papers, 2015 to 2020). "Observations of reduced circulating levels of IL-6 and pro-inflammatory Ly6Chigh monocytes in ApoE/mdx mice also suggested a general dampening of inflammatory activation as a result of dystrophin deficiency." (PMID 26345322, 2015). "Additionally, we observed a relative decrease in the spleen T cell content as well as reduced levels of T cell-derived cytokines in plasma in ApoE/mdx mice suggesting that dystrophin deficiency may influence the development of the immune system." (PMID 26345322, 2015). "Immunofluorescence microscopy clearly confirmed the drastic reduction of ApoE in the mdx-4cv spleen and indicated that the expression of the short spleen-associated isoform of dystrophin is not affected in dystrophinopathy." (PMID 32916630, 2020).
encephalitis (3 papers, 2022 to 2025). An acute inflammatory process affecting the brain parenchyma. "Males showed higher susceptibility to severe encephalitis compared to females, consistent with the notion that genetic (e.g. ApoE gene) and metabolic factors exhibit sex-specific differences that influence the susceptibility to neuroinflammatory disease." (PMID 40517242, 2025).
exfoliation syndrome (3 papers, 2009 to 2024). An autosomal dominant disorder caused by mutations in the LOXL1 gene, encoding lysyl oxidase homolog 1. "Another study in Greek patients reported no APOE association in pseudoexfoliation syndrome (PXS)/PXG but found an increased risk of POAG in APOE ε2-carriers." (PMID 38674156, 2024).
gallbladder disease (3 papers, 2011 to 2023). "The association of APOE isoforms with gallbladder disease was the opposite in men and women." (PMID 21941641, 2011).
gallstones (3 papers, 2014 to 2025). Solid crystalline precipitates in the biliary tract, usually formed in the gallbladder, resulting in the condition of cholelithiasis. "For instance, the ApoE E4 allele, which is more prevalent in Mexican Americans, confers susceptibility to gallstones." (PMID 39944962, 2025). "Research with APOE-deficient mice showed decreased gallstone formation compared to the wild-type mice, suggesting a role of APOE in gallstone formation." (PMID 31200656, 2019). "For example, a positive association was found between APOE E4 genotype and cholesterol crystals in bile, fast cholesterol crystallization in gallbladder bile and a higher cholesterol content in gallstones." (PMID 31200656, 2019).
gastric tumors (3 papers, 2019 to 2024). "The study indicates that macrophages with high APOE expression are enriched in metastatic gastric tumors, contributing to immune evasion by reducing CD8+ T cell infiltration." (PMID 39763652, 2024). "Similarly, M2 macrophages-secreted exosomes can promote the dissemination of gastric tumor cells by selectively transferring apolipoprotein E (ApoE), and ApoE can reshape cytoskeleton-supporting transportation by activating the PI3K-Akt signaling pathway." (PMID 30925925, 2019).
geographic atrophy (3 papers, 2014 to 2022). "We next performed APOE staining on paraffin sections of controls and donor eyes with geographic atrophy lesions." (PMID 25604058, 2015). "Genes with common risk alleles associated with geographic atrophy and neovascular AMD were upregulated in geographic atrophy RPE cells, including CFH, HTRA1, EFEMP1, and APOE, which provide further evidence of their involvement in the pathogenesis of geographic atrophy." (PMID 35882847, 2022).
gestational diabetes (3 papers, 2022 to 2024). Carbohydrate intolerance first diagnosed during pregnancy. "Age, pre-pregnancy BMI, FPG, PT, INR, APTT, FIB, TT, D-Dimer, TC, TG, LDL-C, sdLDL-C, APOB, and APOE were all predictors of gestational diabetes in the study population (P < 0.05)." (PMID 35387184, 2022). "In gestational diabetes mellitus (GDM) patients, CEC of maternal GDM-HDL is 25% lower than that of healthy HDL, which is found to be positively correlated with the PON1 activity and contens of APOA1 and APOE." (PMID 37386457, 2023).
herpes simplex (3 papers, 2010 to 2021). "In females, network-based analysis revealed a coordinated program of gene expression involving several zinc finger nuclease genes related to Herpes simplex viral infection whose expression was modulated by the presence of the APOE ε4 allele." (PMID 34658838, 2021).
intervertebral disc degeneration (3 papers, 2017 to 2024). "Interestingly, APOE-knockout rabbit exhibits susceptibility to premature intervertebral disc degeneration." (PMID 34366712, 2021). "ApoE is involved in lipoprotein metabolism and ApoE -/- mice showed intervertebral disc degeneration partially due to increased matrix metalloproteinase (MMP) -3, -9, and -13 levels." (PMID 38802922, 2024).
Intraventricular hemorrhage (3 papers, 2021 to 2023). Bleeding into the ventricles of the brain. "Despite our efforts, unmeasured confounders might exist that might not have been included in the multivariable analyses, for instance, CT angiographic spot sign, volume of intraventricular hemorrhage and apolipoprotein E genotype." (PMID 34446807, 2021).
lipidosis (3 papers, 2015 to 2023). "In conclusion, ApoE deficiency acts synergistically with a WD to trigger lung lipidosis and inflammation at least in part via TLR4 signaling." (PMID 25975841, 2015). "The present study demonstrated that ApoE deficiency in combination with a WD induces lipidosis and chronic inflammation in lungs through the TLR4 pathway." (PMID 25975841, 2015). "Research has shown that the C-terminal domain of APOE is the key to lipoprotein binding and determines the specificity of APOE subtype lipidosis." (PMID 38002514, 2023). "The pathogenesis of the ApoE knockout combined with a HFD also results in lipidosis and inflammation in lung tissue through the toll-like receptor 4 (TLR4) pathway." (PMID 35172845, 2022). "The results showed that ApoE−/− mice developed lung lipidosis following 12 weeks of receiving a WD, as evidenced by an increased lung cholesterol content." (PMID 25975841, 2015). "The results of the present study revealed that lung lipidosis occurred in the ApoE−/− mice receiving the WD for 12 weeks." (PMID 25975841, 2015). "The results of the present study showed that TLR4 signalling activated the MyD88/NF-κB and the TRIF/IRF3 pathway to elicit lung inflammation and lipidosis in the ApoE−/− WD mice." (PMID 25975841, 2015). "The aim of the present study was to determine whether ApoE deletion combined with hypercholesterolemia induces lung inflammation and lipidosis." (PMID 25975841, 2015). "Blocking the TLR4 pathway was able to ameliorate lipidosis and inflammation in the ApoE−/− WD mice." (PMID 25975841, 2015). "By contrast, ApoE−/− ND or wild-type WD mice exhibited low-grade or no inflammation and mild lipidosis." (PMID 25975841, 2015).
lipodystrophy (3 papers, 2019 to 2025). A congenital or acquired disorder characterized by abnormal loss or redistribution of the adipose tissue in the body. "Here, we aimed to explore the effects of adipose transplantation on lipodystrophy-associated metabolic cardiovascular diseases in Seipin knockout mice crossed into atherosclerosis-prone apolipoprotein E (Apoe) knockout background." (PMID 38525541, 2024).
lobar intracerebral hemorrhage (3 papers, 2007 to 2022). An intracerebral hemorrhage occuring within the cerebral lobes, either in the cerebral cortex or in the cortical-subcortical junction. "Previous studies have demonstrated that APOE ε4 and/or APOE ε2 are associated with lobar intracerebral hemorrhage (ICH)." (PMID 17672902, 2007).
meningitis (3 papers, 2022 to 2025). A disorder characterized by acute inflammation of the meninges of the brain and/or spinal cord. "Here, we report APOA5 to be associated with meningitis, while previous studies implicated various other apolipoproteins, such as APOA1 and APOE, are involved in meningitis, as well as various bacterial or respiratory infections, both in human and mouse studies." (PMID 37108169, 2023). "A significantly higher expression of APOAI, APOB, and APOE in patients with TBM than those with other infectious meningitis indicated that the occurrence and progression of TBM are related to abnormal lipid metabolism." (PMID 36003300, 2022).
metastatic tumors (3 papers, 2019 to 2025). "We examined APOE expression in histological slides of lymph node tissues containing metastatic tumours." (PMID 39810624, 2025). "We found that myeloid components in human metastatic tumors were mainly composed of monocytes and TAMs, and all three TAM clusters highly expressed lipid-associated TAM markers (APOE, C1QA, and TREM2) and exhibited a pro-tumoral phenotype featured by CD206 (MRC1) expression." (PMID 40394007, 2025). "Histological analysis showed lung metastatic tumors were less-differentiated in ApoE KO mice." (PMID 31275318, 2019). "To further validate the clinical relevance of APOE expression in metastatic PTC, we investigated APOE expression in a cohort of 41 patients with metastatic disease." (PMID 39810624, 2025).
nephrosis (3 papers, 2014 to 2024). Pathological processes of the KIDNEY without inflammatory or neoplastic components. "Plasma accumulation of ApoE-rich lipoproteins in nephrosis resulted in exposure of podocytes to relatively high concentrations of these lipoproteins." (PMID 33633132, 2021).
Niemann-Pick disease (3 papers, 2014 to 2025). A group of inherited, severe metabolic disorders in which sphingomyelin accumulates in lysosomes in cells. "The apolipoprotein E protein is associated with Alzheimer (M104310+) and heart disease (M617347), the NPC1 cholesterol trafficking regulator responsible for CNS lipid accumulation in Niemann–Pick disease (M257250)." (PMID 37504295, 2023).
occlusive vascular disease (3 papers, 2022). "Regardless, these data documented that apoE regulates endothelial cell functions in an isoform-dependent manner and established one mechanism by which apoE is protective against vascular occlusive diseases." (PMID 36077289, 2022). "In addition to its role in modulating smooth muscle cell migration and proliferation to suppress vascular occlusive diseases, apoE also plays an important role in maintaining vascular biomechanics under normal conditions." (PMID 36077289, 2022). "Cholesterol ester CE(18:2), additionally identified in our study as ApoE-specific plaque biomarker, was also previously detected in aortic roots of ApoE−/− mice at 60 weeks of age and in femoral arteries of humans with peripheral artery occlusive disease using MSI." (PMID 34797426, 2022).